FOXP3 (forkhead box P3)
Diseases named in the same sentence as FOXP3 in open-access papers (continued):
Sharing a sentence is not in itself a finding about the gene and the disease.
colitis (continued). "Taken together, these data suggest that the combined loss of iNKT cells and dysregulated IFNγ production can induce a decrease in protective Foxp3+CD25+CD4+ T cells during DSS-induced colitis." (PMID 30333822, 2018). "Early data suggest that, in addition to Foxp3 Tregs, cecal bacterial extract-pulsed DC protect from experimental colitis by generating Tr1 Tregs." (PMID 29774025, 2018). "The expression of Foxp3 protein was significantly decreased in the colitis group compared with the normal group (P < 0.001) as well as the pretreated-Bifico-colitis group (P < 0.05)." (PMID 29849501, 2018). "In particular, a single dose of 25 μg·kg−1 of TCDD reduced the colitis symptoms through the activation of the AhR pathway, leading to a differential expression of the pathology-involved genes, i.e., Foxp3 and IL-17." (PMID 30567322, 2018). "Alpinetin (15, 30 mg/kg) significantly up-regulated levels of IL-10 and Foxp3 in colons of colitis mice." (PMID 30166541, 2018). "In the present study, we found that LC27 and LC67 inhibited Th17 cell differentiation and RORγt expression, and enhanced Treg differentiation and Foxp3 expression, leading to attenuation of colitis and liver injury." (PMID 29760423, 2018). "We found that enrichment of Rikenella and Alistipes (Rikenellaceae) in Nod2−/− mice at 8 weeks of age reared separately was associated with increased proportion of CD4+ LAP+ Foxp3− cells and less severe TNBS-colitis." (PMID 30250234, 2018). "In fact, the number of Foxp3+ Tregs in colonic tissue was increased by the administration of Bifico in pretreated-Bifico-colitis and pretreated + treated-Bifico-colitis groups compared with the colitis group." (PMID 29849501, 2018). "In conclusion, treatment with the combination of a probiotic complex, prebiotics, rosavin, and zinc attenuated colitis, significantly decreased the levels of proinflammatory cytokines, and significantly increased the levels of Foxp3 and IL-10 in colon tissue." (PMID 29466999, 2018). "The methylation level of Foxp3 promoter region in colons of colitis mice was inhibited by alpinetin (15, 30 mg/kg) treatment." (PMID 30166541, 2018). "Although DSS colitis is mainly an innate immunity-driven condition, our study adds to the growing body of evidence showing that Foxp3+ Treg and IL-10 Bregs can suppress a mainly innate-driven inflammation." (PMID 29774025, 2018). "Further, these findings suggest that B. fragilis is involved in a distinct preventive mechanism against intestinal inflammation in carcinogen/DSS-induced CRC compared to regulation by IL-10 or Foxp3 in T-cell transfer or a TNBS colitis model." (PMID 30429227, 2018). "Our results suggest that PGE2 secreted from fAT-MSC can reduce inflammation by increasing FOXP3+ Tregs in mice model of colitis." (PMID 30453939, 2018). "In agreement, it has been shown that corticosteroid treatment leads to the up-regulation of coinhibitory molecules such as CTLA‐4, PD‐1, CD73, and FOXP3 in a colitis model." (PMID 30550561, 2018). "Recent studies have shown that Clostridia clusters XIVa, IV derived from human feces have the potential to induce Foxp3+ Tregs and are able to suppress inflammatory conditions such as colitis, experimental autoimmune encephalomyelitis, and multiple sclerosis." (PMID 29969462, 2018). "We have also identified that deficiency of paracrine mPGES1-driven PGE2 exacerbates T cell-driven colitis by selectively decreasing CD4+FoxP3+ cells in the mLN, with a concomitant increase of total number of CD4+ infiltration in the cLP." (PMID 30619314, 2018). "Onji and colleagues have reported that carbonic anhydrase I-pulsed bone marrow-derived DC generated in vitro with GM-CSF/IL-10/TGF-β inhibited colitis progression via rebalancing the Foxp3+/TH17 T-cell ratio inside the MLN." (PMID 29774025, 2018).
colitis (continued). "The increased methylation of CpG islands (CpGs) of Foxp3 promoter and the demethylation of CpGs of IL-17 promoter, due to acute colitis induced in C57BL/6 mice, were reversed after TCDD treatment." (PMID 30567322, 2018). "Transcriptional factor Foxp3 is a lineage specification factor of Tregs that has been shown to prevent the development of colitis in a T cell transfer model of colitis." (PMID 30697218, 2018). "For instance, butyrate increases the differentiation of colonic regulatory T cells by changing histone H3 acetylation of the Foxp3 promoter, and this results in protection against colitis development." (PMID 29362450, 2018). "Simultaneously, MMDP treatment markedly increased the percentage of CD4+ Foxp3+ (Treg cells) when compared with untreated TNBS-induced colitis group." (PMID 28946886, 2017). "Continuous CD40-signalling disables CD103+ DCs to induce RORγt+Foxp3+ iTreg cells and causes accumulation of IL-17A+IFN-γ+ Th17/Th1 T cells, breakdown of tolerance to gut microbiota, dysbiosis and fatal colitis." (PMID 28276457, 2017). "Here, we investigated the role of the protein AMI-1 on Foxp3 expression and its influence on Tregs function in a colitis mouse model and in patients with UC." (PMID 28588584, 2017). "By increasing the number of T cells expressing Foxp3 in the colon, H. polygyrus infection was shown to protect mice in some models of experimental colitis." (PMID 28938014, 2017). "We demonstrated that FOXP3 expression was suppressed by DSS-induced colitis, but intriguingly curcumin treatments, ETO-curcumin in particular, reversed this suppression." (PMID 28400554, 2017). "Although TRAF-6-knockout Tregs had similar inhibitory activity to wild-type Tregs in vitro, the reduced number of Foxp3-positive cells suggests that TRAF-6 knockout cannot suppress the development of colitis in mice with lymphopenia." (PMID 28219358, 2017). "Administration of recombinant IFN-α ameliorated T-cell-dependent colitis by augmenting the number of Foxp3+ Tregs suggesting a potential therapeutic application of type I IFN in intestinal inflammation." (PMID 28352268, 2017). "Depletion of Foxp3+ Treg exacerbates intestinal inflammation even in the T-cell-independent colitis model." (PMID 26908454, 2016). "Our findings are consistent with a report by Murai and colleagues showing that secretion of IL-10 by myeloid cells helps maintain Foxp3+ Tregs in a model of colitis." (PMID 26756215, 2016). "Simultaneously, Foxp3+ Treg require IL-10 signals to maintain their regulatory function to prevent colitis." (PMID 27027442, 2016). "Similar outcomes of CD4+CD25− Foxp3+ T cells and their functions were reported in animal models of experimental colitis." (PMID 26728323, 2016). "In vivo studies demonstrated a significantly lower percentage of CD25 + Foxp3+ Tregs in the peripheral blood of rats from the TNBS-treated colitis group than in the control group." (PMID 27473867, 2016). "In line with our expectation, the colitis resistant BALB/c mice had a higher percentage of FoxP3+CD25+ Treg cells (measured as percentage from all T cells) in their spleen." (PMID 27051505, 2016). "GATA-3 and Foxp3 were expressed more highly in mice of group TNBS-rSjcystatin than in mice with colitis, while a low expression of T-bet was seen after rSjcystatin treatment except that RORγ(t) stayed nearly the same in those two experimental groups." (PMID 26728323, 2016). "In a chronic colitis model, greater infiltration of Foxp3+ regulatory T (Treg) cells was seen in the colon of CD200tg mice compared to WT mice, and anti-CD25 mAb given to these mice attenuated protection." (PMID 26841120, 2016). "Our findings support a model whereby the interplay between B lymphocytes and a diversified naïve T cell repertoire is critical for the generation of CD4+CD25+Foxp3+ pTreg cells and colitis suppression." (PMID 27353032, 2016). "Tlr5−/− mice develop spontaneous colitis, despite an increased number of Foxp3+ Tregs compared to WT littermates." (PMID 26583115, 2015).
colitis (continued). "Taken together, these data indicate that the regulatory effects induced by TCRγδ+LAP+ cells in DSS colitis is related to an increase of the Foxp3+ Treg cell compartment as well as production of anti-inflammatory and epithelium protective cytokines." (PMID 26644347, 2015). "Supporting these findings, the immunomodulatory effect of a polysaccharide A from Bacteroides fragilis was directly correlated with TLR2-signalling and increased FoxP3+Treg cells secreting IL-10 in an experimental model of TNBS-induced colitis." (PMID 25853847, 2015). "The CTX treatment in TNBS-mice also induced a secretion of TGF-β, IL-10, PGE2 and LXA4 accompanied by CD4+FoxP3+ cells, suggesting their participation in the improvement of the colitis induced by TNBS." (PMID 25853847, 2015). "Our results showed that the colonic protein and mRNA expression levels of T-bet and ROR-γt significantly decreased but GATA-3 and Foxp3 expressions were enhanced in colon after HQT treatment in colitis rats." (PMID 26347453, 2015). "It has been demonstrated that a deficiency in CD69 leads to increased production of pro-inflammatory cytokines (such as TNF-α, IFN-γ, and IL-21), reduced FoxP3+ regulatory T-cell function, impaired oral tolerance, and more severe colitis." (PMID 26206376, 2015). "It is possible that analysis of CD4+Foxp3+ cells at earlier stages in the DSS-induced colitis model would show Treg cell expansion induced by TCRγδ+LAP+ cell treatment in the colonic lamina propria." (PMID 26644347, 2015). "In summary, we found that in vivo TCRγδ+LAP+ cells ameliorate colitis by promoting the induction of Foxp3 Treg cells." (PMID 26644347, 2015). "Even though it is protective factors in colitis, with suppressive functions through IL-10 and FOXP3." (PMID 25651850, 2015). "The role of FoxP3+ Treg cells preventing colitis mediated by Th1 and Th17 cells was also proven in an experimental model with the transfer of naive CD4 +T cells to SCID mice." (PMID 25853847, 2015). "Consistent with this, T cell-specific or FoxP3+ Treg-specific deletion of Il10 results in spontaneous colitis, highlighting the importance of Treg-derived IL-10 in preventing intestinal inflammation." (PMID 25944983, 2015). "Recent studies have shown that the development of colonic Foxp3+ Tregs in mice is induced by gut clostridial bacteria and their metabolites, and that these Tregs play a key role in the prevention of colitis." (PMID 26500657, 2015). "Splenic TCRγδ+LAP+ cells appear to play an important role in inducing CD4+Foxp3+ cells and controlling colitis because, although there is a lower frequency of TCRγδ+LAP+ cells in the spleen, the absolute number of TCRγδ+LAP+ cells is 5-fold more than in SI-LP." (PMID 26644347, 2015). "Like CTLA-4, IL-10 has previously been suggested to be important not only as a mediator of suppression for Foxp3+ iTreg cells but also to enhance stable Foxp3 expression in CD4+ T cells in a murine model of colitis." (PMID 25238105, 2014). "In the lesions of DSS-induced colitis in WT mice, FoxP3+ cells were observed among the infiltrating cells but at a very low frequency." (PMID 24743300, 2014). "The CD3e+CD4+CD25+FOXP3+ Tregs were significantly induced in the MLN cells from the mice with DSS-induced colitis followed with T. spiralis AES treatment compared to the DSS-induced mice (P<0.05)." (PMID 24788117, 2014). "Intracellular staining of FoxP3 in spleen-derived CD4+ T-cells of mice with T-cell transfer-induced colitis showed enhanced numbers and percentages of FoxP3pos cells, i.e. iTregs, in mice that had received β2i/MECL-1&β5i/LMP7-deficient CD4+ T-cells." (PMID 24740379, 2014). "Actually in the present study, the frequency of FoxP3+ cells was significantly increased in parallel with significantly attenuated inflammatory reaction in the lesions of DSS-induced colitis in mice with elevated level of ROS due to defects in GPx1 and Cat." (PMID 24743300, 2014).
colitis (continued). "Together with our present results that inflamed colon of IL-17KO mice contained reduced levels of Foxp3+ T cells, it is also possible that CD11b+Ly6C+MHC Class II+ macrophages ameliorate colitis through enhancement of Foxp3+ regulatory T cell function." (PMID 25254662, 2014). "In mice, gut Clostridium bacteria are potent inducers of colonic interleukin (IL)-10-producing Foxp3 regulatory T cells (Treg), which play key roles in the prevention of colitis and in systemic immunity." (PMID 24714093, 2014). "By contrast, in the lesions of DSS-induced colitis in GPx1−/− × Cat−/− mice, FoxP3+ cells were observed quite frequently among the infiltrating cells." (PMID 24743300, 2014). "Our previous studies demonstrated that PG reduces TNF-α production and induces Foxp3+ Treg cells in colitis and EAE mouse models." (PMID 25032213, 2014). "During colitis, Lb CNRZ327 modulated the production of TGF-β, IL-6, and IL-12 in colonic tissue and of TGF-β and IL-6 in the spleen, and caused an expansion of CD4+Foxp3+ regulatory T cells in the cecal lymph nodes." (PMID 24465791, 2014). "In rodent hapten-induced colitis, disease severity is worsened by subdiaphragmatic vagotomy, correlated with reductions in FoxP3+ Tregs." (PMID 25110981, 2014). "We found that Mst1 is required for the suppression of T cell–induced colitis and T cell proliferation in vitro by natural Foxp3+ CD4+ Treg cells." (PMID 24040101, 2013). "In contrast, in our present study using a model of DSS-induced colitis, the FoxP3+ regulatory T cells migrated normally in the inflamed tissue, and impaired colitis was observed in both the acute and chronic models of colitis." (PMID 23785429, 2013). "Further, the depletion of Foxp3+ Treg from Foxp3-GFP-DTR mice increased the severity of acute dSS-colitis accompanied by 80% lethality of Treg-depleted mice." (PMID 22849659, 2012). "The influence of Foxp3+ Treg on intestinal inflammation was tested using the CD4+ T-cell transfer colitis model in Rag−/− C57BL/6 mice and the acute DSS-colitis model." (PMID 22849659, 2012). "In accordance with the loss in body weight following the deletion of Foxp3+ Treg, we observed death of 40% of mice that developed chronic transfer colitis as a result of Foxp3+ Treg deletion, whereas all mice with Foxp3+ Treg survived." (PMID 22849659, 2012). "Further, deletion of Foxp3+ Treg built the basis for the development of severe acute DSS-colitis and chronic T cell-mediated intestinal inflammation." (PMID 22849659, 2012). "We observed demethylation of CpG islands present in the Foxp3 promoter and increased methylation of CpG islands of the IL-17 promoter, following activation of AhR during colitis." (PMID 21858153, 2011). "This is in contrast to the role of integrin αvβ8-mediated TGF-β activation, because mice lacking this TGF-β–activating integrin on DCs not only show reduced levels of lamina propria Foxp3+ Tregs, but also develop severe colitis under steady-state conditions." (PMID 21723222, 2011). "In this context, the current study demonstrates, using TCDD, how AhR activation leads to selective upregulation of FoxP3+ Tregs and down regulation of Th17 cells through epigenetic regulation, leading to amelioration of an inflammatory disease such as colitis." (PMID 21858153, 2011). "Analysis of MLN or LP cells during colitis revealed increased methylation of CpG islands of Foxp3 and demethylation of IL-17 promoters, which was reversed following TCDD treatment." (PMID 21858153, 2011). "Studies using mice in a Trinitrobenzene Sulfonic Acid (TSA) induced colitis model, treated with Vitamin D and dexamethasone, show that the combined use of Vitamin D and dexamethasone enhanced Foxp3 expression accompanied by the induction of IL-10 and TGF-beta." (PMID 21829599, 2011). "CD4+Foxp3+ Tregs were able to control Th17 and Th17+Th1 cells in an IL-10-dependent manner in mice colitis." (PMID 22032685, 2011).
colitis (continued). "In experimental models of colitis, the appearance of increased numbers of Foxp3+ cells precedes the spontaneous resolution of inflammation, whereas a low number is associated with persistence of inflammation." (PMID 20706593, 2010). "Mechanistically, isobutyrate can increase the relative abundance of Lactobacillus reuteri, thereby increasing the production of indole-3-lactic acid, regulating aryl hydrocarbon receptor expression and downstream signaling pathways, and regulating Foxp3+ CD4+ T cell recruitment to alleviate colitis." (PMID 40342298, 2025). "Similarly, in the DSS-induced colitis model, Gpr15−/− mice presented significantly lower Foxp3 expression in the colon than did Gpr15+/+ mice." (PMID 40957881, 2025). "Nevertheless, a recent study suggested that Helicobacter ganmani and the augment of Helicobacter enhanced the induction of RORγt+ Foxp3+ iTregs cells which improved the resistance against DSS-induced colitis in a fecal microbiota transplant (FMT) model pretreated with glycerol monolaurate." (PMID 39641861, 2025). "FFAR2 signaling is necessary for SCFA-driven expansion of colonic Foxp3^+ regulatory T cells and protection from T-cell-transfer colitis, while SCFAs additionally act via HDAC inhibition and mTOR–S6K modulation to stabilize Foxp3 expression and limit pro-inflammatory Th17 responses." (PMID 41293163, 2025). "Indeed, B. fragilis secretes the immunomodulatory molecule polysaccharide A (PSA) via outer membrane vesicles, which facilitates the conversion of naïve CD4+ T cells into FOXP3+ Tregs, ultimately protecting mice from experimental colitis." (PMID 40309194, 2025). "Moreover, in mice with dextran sulfate sodium salt (DSS)-induced colitis, diminished manifestation of Egr-1 and Foxp3 was discerned in colon tissue (P < 0.01 and P < 0.001)." (PMID 40235598, 2025). "Moreover, OPN sustains proper expression of Foxp3 on regulatory T cells in the intestine and therefore, protect against colitis." (PMID 38455042, 2024). "Previously, SEA has been shown to significantly reduce the severity of 2,4,6-trinitrobenzene sulfonic acid (TNBS)-induced colitis and dextran sulfate sodium (DSS)-induced colitis in a mouse model by increasing the number of FoxP3+ Treg cells and secretion of Th2 cytokines, including IL-10." (PMID 39481080, 2024). "Similarly, B. pseudolongum supplementation was also found to be able to attenuate colitis by increasing the intestinal proportion of Foxp3+T cells and modulating the Pparγ/STAT3 pathway in DSS-fed mice." (PMID 39275234, 2024). "Therefore, Dub colonization promotes the production of the Trp catabolite Kyn, which induces CD25+Foxp3+Tregs to exert a protective effect on DSS-induced colitis." (PMID 38351003, 2024). "These Foxp3+ Rorγt+ Tregs contribute to immune tolerance of the microbiota and suppress colitis." (PMID 38730492, 2024). "However, in previous work, Foxp3-specific deletion of IL-10 resulted in only modest colitis compared with the severe colitis observed in IL-10KO mice." (PMID 37314833, 2023). "Myeloid-ILK deficient mice showed enhanced tumour infiltration of CD8+ T cells and reduced tumour infiltration of FOXP3+ T cells in colitis-associated and APCmin/+-driven CRC, respectively, with an overall elevated CD8+/FOXP3+ ratio suggesting an anti-tumour immune phenotypes." (PMID 38077324, 2023). "Despite that glutamine supplementation attenuates intestinal inflammation in the DSS-induced colitis animal model, Foxp3+ T cells induced by glutamine restriction have shown superior immunosuppressive capacity in vivo to prevent IBD using the adoptive T cell transfer mouse model." (PMID 37809060, 2023). "ERK signaling downregulated the expression of FOXP3 by Treg cells in a mouse model of colitis." (PMID 36768873, 2023).